EIF4G1 (eukaryotic translation initiation factor 4 gamma 1)
Diseases named in the same sentence as EIF4G1 in open-access papers (continued):
Sharing a sentence is not in itself a finding about the gene and the disease.
infection (80 papers, 2008 to 2026). The state of being infected such as from the introduction of a foreign agent such as serum, vaccine, antigenic substance or organism. "Further IFN and antiviral related proteins were upregulated upon infection with PeV-A3 (EIF2AK2, STAT1), or PeV-A1 (NCAM1, POM121), and downregulated upon PeV-A1 infection (EIF4G1, UBE2N, RANBP2, FLNA)." (PMID 38514653, 2024). "In other studies, viral suppression of replication was observed after silencing of eIF4G1 protein expression during infections with vesicular stomatitis virus and influenza virus." (PMID 35498732, 2022). "For Ssa13, the Eukaryotic translation initiation factor 4 gamma 1 (EIF4G1), up-regulated 14 days post infection, is one of the closest genes to the most significant SNPs." (PMID 33985436, 2021). "We also performed infection experiments on HeLa cells for 36hours and investigated SG formation using immunofluorescence (IF) assays with specific antibodies against other SG markers, including eIF4E, eIF4G1, and PABP1." (PMID 38935808, 2024). "According to our analysis above, the difference between YN13 and YN144 in replication ability might be due to the difference between the two PEDV-infection groups in alterations of eIF4G1, hnRNPA1, HSP90B1, HSP90AB1, HSPA8, DNAJA1, and DNAJC10 in jejunums of pigs." (PMID 27916855, 2016). "At late stages of infection, the ASFV protein pA224L induces the expression of eIF4G1 and eIF4E subunits of the eIF4F complex." (PMID 39123713, 2024). "At late times of infection, the IAP homolog ASFV protein A224L induces the expression of eIF4G1 and eIF4E subunits of the eIF4F complex." (PMID 37631977, 2023). "When interrogating the Vis AD cell proteome for proteins involved in the “interferon signaling” pathway, we found seven proteins altered by infection with CoV-2(P.1), among which five were upregulated (i.e., IRF1, HLA-C, TPR, EIF4G1, and TRIM28)." (PMID 36175400, 2022). "The closest gene to the most significant SNPs showing differential expression is the Eukaryotic translation initiation factor 4 gamma 1 (EIF4G1), which was up-regulated 14 days post infection." (PMID 33985436, 2021). "Upon infection, the expression of EIF2A, EIF3D, EIF4G1, and EIF4A was increased." (PMID 38674742, 2024). "IFNα challenge prior to CAV21 infection (16 h) did not prevent eIF4G1 cleavage and delayed viral translation modestly; yet, it abolished PVSRIPO translation." (PMID 35652592, 2022). "mOVA2 infection of GMCSF- and FLT3L-BMDCs revealed the absence of eIF4G1 cleavage, the hallmark of poliovirus cytopathogenicity." (PMID 31988324, 2020). "Interestingly, in the absence of infection, we observed endogenous proteolysis of proteins known to be cleaved by enteroviruses, including DDX6, HNRPM, EIF5B, G3BP1, and eIF4G1/2." (PMID 38918600, 2024).
cancer (72 papers, 2007 to 2026). A tumor composed of atypical neoplastic, often pleomorphic cells that invade other tissues. "The silencing or the inhibition of EIF4G1 caused decreased cyclin D1 and Rb protein levels, cell cycle delay, reduced cell viability, proliferation, clonogenic activity, cancer spheroid formation, as well as increased sensitivity to chemotherapeutic drugs." (PMID 32659970, 2020). "We next analyzed the data through cBioPortal for alteration frequency of EIF4G1 based on mutation, fusion, amplification, deep deletion and multiple alternations across human cancer." (PMID 31496918, 2019). "In humans, the overexpression of eIF4G1 is implicated in cancer and oncogenesis, whereas In yeast and nematodes eIF4G1 is found to be vital to organism development, wherein knock out of eIF4G1 is detrimental." (PMID 30740222, 2019). "We further analyzed that EIF4G1 mRNA expression in provisional TCGA datasets across multiple cancer types with the different mutational patterns." (PMID 31496918, 2019). "Aberrant over-expression of EIF4G1 is tightly linked with the prognosis of several cancers, such as lung squamous cell carcinoma, inflammatory breast cancer, cervical cancers, and nasopharyngeal carcinoma." (PMID 30970654, 2019). "Targeting cap-dependent translation via EIF4G1 scaffold can disrupt the expression of multiple oncogenic pathways that are associated with tumor progression, offer an excellent target in therapy-resistant cancers." (PMID 31496918, 2019). "Mechanistically, loss of PAK1 promoted mRNA decay and inhibited the expression of CD44, SAA1, MTOR, RPS6KB1, and EIF4G1, the factors involved in tumorigenesis in many cancers." (PMID 41459112, 2026). "Eukaryotic translation initiation factor 4 gamma 1 (EIF4G1) is highly expressed in many cancers and affects their occurrence and development." (PMID 36897548, 2023). "Overexpression of EIF4G1 promotes the proliferation, invasion, migration, apoptosis and tumorigenesis of cancer cells." (PMID 36897548, 2023). "Eukaryotic translation initiation factor 4 gamma 1 (EIF4G1) expression is increased in different types of cancers." (PMID 36551184, 2022). "Immunohistochemistry (IHC) was applied to compare the protein levels of EIF4G1 in normal and cancer tissues and to verify the prognostic value of EIF4G1." (PMID 36551184, 2022). "We found that EIF4G1 expression was closely correlated with tumour differentiation; EIF4G1 expression in poorly differentiated tumour tissues was significantly higher than that in moderately and well‐differentiated cancer tissues, P < .001." (PMID 33523588, 2021). "By using cancer patients tissue assays, the results indicate that EIF4G1 expressional levels are much higher in NSCLC tissues than in adjacent or normal lung tissues, which are also associated with NSCLC patient survival." (PMID 33539648, 2021). "The results showed that EIF4G1 expression was significantly higher in cancer tissues than in paired adjacent normal lung tissues." (PMID 33523588, 2021). "Here, we found that EIF4G1 has close associations with some immune checkpoint molecules such as PD‐1 and PD‐L1 in NSCLC by using RNA‐Sequencing and tissue arrays data from cancer patients." (PMID 33539648, 2021). "Up to date, several EIF4G1‐targeted molecular inhibitors have been developed and tested in treatment of cancer." (PMID 33523588, 2021). "As deletion of Arf is a common occurrence in cancer, exploring the co-occurrence of Arf-loss and increased LARP1 or eIF4G1 expression seems warranted." (PMID 33335292, 2020). "Increased expression of EIF4G1, described in several types of human cancers, promotes tumor cell proliferation through the modulation of the MNK1–eIF4G–eIF4E signaling pathway." (PMID 32659970, 2020). "Previous studies reported that EIF4G1 was confirmed to be highly expressed and regulated the progression of various cancers, including PCa." (PMID 32943997, 2020).
cancer (continued). "Among these, we found an overlap in the amplification frequencies of three different snoRNA/host gene couples, namely SNORA63/EIF4A2, SNORA63E/LINC00888, SNORD66/EIF4G1, in five different cancer types: HNSC, KIRC, SKCM, OV, and GBM." (PMID 32046192, 2020). "Examination of EIF4G1 protein in the tissue sections by IHC, revealed an increase in EIF4G1 protein levels in cancer tissues (right side) derived from different organs viz." (PMID 31496918, 2019). "We analyzed the EIF4G1 mRNA levels across human cancer cell lines derived from different organs through DepMap portal and found an elevated expression in EIF4G1 across different human cancer cell lines." (PMID 31496918, 2019). "Our analysis of the TCGA data revealed that EIF4G1 mRNA expression is significantly increased in tumor tissues compared to respective control tissues across human cancers and variable expression was observed among different datasets." (PMID 31496918, 2019). "Summarizing the data based on depletion assay (CRISPR-Cas9, shRNA/siRNA) through DepMap showed the dependency of EIF4G1 for cancer cells survival." (PMID 31496918, 2019). "Overall, data showed overexpression of EIF4G1 mRNA across human cancers that is in-line with the findings from IHC data for EIF4G1." (PMID 31496918, 2019). "Results of genome-wide CRISPR-Cas9 screens with the Avana sgRNA library in 341 cancer cell lines showed EIF4G1 dependency across human cancers." (PMID 31496918, 2019). "We found an elevated level of EIF4G1 (6 to 11 fold increase) across human cancers as compared to normal tissue samples." (PMID 31496918, 2019). "This is the first study demonstrating overexpression/amplification of EIF4G1 across pan-cancers, highlighting a broader role for EIF4G1." (PMID 31496918, 2019). "Altogether, data suggested that there is a high expression of EIF4G1 mRNA levels across human pan-cancers." (PMID 31496918, 2019). "Our analysis of the TCGA data by using Ualcan and c-bioportal server revealed the higher expression of EIF4G1 mRNA expression across human cancers." (PMID 31496918, 2019). "In the current study, we analyzed the role and expression of EIF4G1 in Pan human cancer panels through various approaches." (PMID 31496918, 2019). "Data analysis of EIF4G1 and dependency on cancer cell survival, we analyzed the dataset through DepMap based on shRNA (or siRNA) inhibition for EIF4G1 in combined RNAi from Broad, Novartis and Marcortte datasets." (PMID 31496918, 2019). "We analyze the EIF4G1 mRNA expression data and found a lower levels of EIF4G1 expression across normal tissues derived from different organs as compared to mRNA expression data for EIF4G1 in cancer tissues from pan-cancers." (PMID 31496918, 2019). "We also analyzed the EIF4G1 protein level by western blot in the multiple human cancer cell lines viz." (PMID 31496918, 2019). "We further explored the functional role of EIF4G1 in cancer cells, we did the clonogenic and tumorosphere assays with 4EGI-1, a known inhibitor of the EIF4G-EIF4E complex in two model cell lines viz." (PMID 31496918, 2019). "We observed an increase in EIF4G1 protein levels in tissue sections from different cancers as compared to their respective normal tissue." (PMID 31496918, 2019). "Western blots for EIF4G1 protein was done for different cell lines in representing the multiple cancer types." (PMID 31496918, 2019). "Immunohistochemistry analysis of EIF4G1 protein was done on high-density multi-organ Human Cancer tissue microarray (TMA) derived from the patient samples from different cancers." (PMID 31496918, 2019). "We also analyzed the cancer dependency (cancer cell viability) based on EIF4G1 status across pan-cancer." (PMID 31496918, 2019). "We tested the functional role of EIF4G1 by treatment with known 4EGI-1 inhibitor and found it impaired the clonogenic and tumorosphere potential in different cancer cell lines resistant to known therapies and also inhibits cancer cell invasion." (PMID 31496918, 2019).
cancer (continued). "We found that EIF4G1 is required for cancer cell proliferation and survival across cancers suggesting the role of EIF4G1 in cancer cell survival across human cancers." (PMID 31496918, 2019). "We analyzed the survival of patients with different cancer based on mRNA expression data for EIF4G1 from TCGA datasets through UALCAN web server." (PMID 31496918, 2019). "We observed an increase in EIF4G1 protein levels in the cancer patient samples that were in-line with EIF4G1 mRNA levels across pan-cancers in TCGA datasets." (PMID 31496918, 2019). "Our analysis of DepMap datasets utilizing depletion assays revealed that EIF4G1 is critical for cancer cell survival." (PMID 31496918, 2019). "In a very recent study in 2017, on 398 cancer cells revealed that eIF4G1 is essential to cancer cell survival." (PMID 29748619, 2018). "While checking TCGA Ovarian cohort (Cancer Genomics Browser) and analyzing the data of Agilent microarray, we found that the patients with high expression of eIF4G1 mRNA have a longer overall survival time (P = 0.004)." (PMID 27668427, 2016). "EIF4G1 has been found overexpressed in a variety of cancers, and playing important roles in cancer pathogenesis, progression, and treatment." (PMID 27003362, 2016). "In addition, immunohistochemical analysis was performed on 128 NSCLC cancer tissues and paired adjacent tissues using a specific anti‐EIF4G1 antibody." (PMID 33523588, 2021). "Although EIF4G1 is overexpressed in a variety of cancers, its role in NSCLC pathogenesis especially immunoregulatory functions, clinical relevance and therapeutic potential remains largely unknown." (PMID 33539648, 2021). "It has been shown that EIF4G1 is upregulated in several human cancers." (PMID 31496918, 2019). "EIF4G1 mRNA and protein levels were high across cancer cell lines from multiple organs." (PMID 31496918, 2019). "We analyzed the requirement of EIF4G1 on cancer cell survival through DepMap portal." (PMID 31496918, 2019). "We used multiple clinical cohorts to analyze the EIF4G1 mRNA expression across human cancers." (PMID 31496918, 2019). "However, further studies are required to develop these concepts and test usefulness of targeting EIF4G1 in cancer using in vivo preclinical model systems, prior to clinical trials in patients." (PMID 31496918, 2019). "Lower DEMETER2 scores show more dependency on EIF4G1 across human cancer." (PMID 31496918, 2019). "Here in the present study, we analyzed the expression and role of EIF4G1 across pan-human cancers." (PMID 31496918, 2019). "Interestingly, several EIF4G1-targeted molecules have been shown promising in experimental cancer treatment." (PMID 27003362, 2016). "Although published literature have demonstrated that EIF4G1 plays important roles in cancer pathogenesis, progression, and treatment, its functional role in NSCLC remains largely unknown." (PMID 27003362, 2016). "Moreover, the marked overexpression of EIF4G1 mRNA across human cancers agreed with findings from immunohistochemistry of an increase in EIF4G1 protein levels in cancer tissues derived from different organs as a result of amplification and/or mRNA up-regulation." (PMID 32659970, 2020). "It is possible that cancer dependency of EIF4G1 and cancer cell survival may depend on the fact that cancer cells are fast growing and high expression of EIF4G1 may be required for rapidly dividing cells, however such considerations cannot explain decrease in tumor invasion." (PMID 31496918, 2019). "Several genes encoding protein products that are important in cancer and have functions related to cell cycle, growth, DNA replication and protein translation (such as CCND1, TOP2A, TOPBP1, TFRC; three members of H4 histone family [HIST1H4C, HIST1H4B, and HIST1H4E]; and EIF4G1)." (PMID 17498291, 2007). "STAB1, EIF4G1, and PLOD3 have been reported to regulate the proliferation, migration, and invasion of cancer cells; however, the role of FAM208A in cancer is unclear." (PMID 37373553, 2023).
cancer (continued). "Except for CDKN1B and RELA, the expression levels of CASP7, CDH3, EIF4G1, and EIF4EBP1 were increased significantly in most individual cancer stages compared with normal samples." (PMID 35787690, 2022). "Among these prognosis related stress granule regulators, EIF4G1, IGF2BP1 had been demonstrated to be key regulators in cancer cells." (PMID 35433677, 2022). "Known cancer drivers NOTCH1, PPP6C, RAC1, EIF4G1, PIK3CA showed significant increase in frequency of SCNA in transition from PPOLs to HNSCC that correlated with their expression." (PMID 31427592, 2019). "Although there are limited studies testing EIF4G1 inhibitors in HNSCC, small molecule inhibitors have been investigated in other cancer types." (PMID 30970654, 2019). "In the NDRG1 module, PSMD2 is overexpressed in many cancer cells, whereas PABPC1, EIF4G1, EIF3H, EIF3E, and EIF3K are RNA translational control members." (PMID 26735889, 2016). "Here, we deepened the study on nine of them (ASS1, EIF4G1, GALNT7, GLUT1, IGF2BP3 (IMP3), ITGA4, RAN, SOD1, and THBS2) to ascertain whether they are truly mesothelial cancer driver genes (CDGs) or genes overexpressed in an adaptive response to the tumoral progression (“passenger genes”)." (PMID 32659970, 2020).
tumor (65 papers, 2002 to 2026). "Intriguingly, only the tumor mutation in EIF4G1 was detected in the sediment and the supernatant of the baseline urine sample." (PMID 32592321, 2020). "Overall, results suggesting the functional role of EIF4G1 in clonogenicity, tumorosphere formation and cell invasion, features associated with tumor progression." (PMID 31496918, 2019). "Our results, presented herein, demonstrate for the first time that increased eIF4G1 expression in PCa was associated with tumor progression." (PMID 29748619, 2018). "We showed for the first time that eIF4G1 expression was increased in PCa and that increased eIF4G1 expression associated with tumor progression and metastasis." (PMID 29748619, 2018). "Moreover, higher EIF4G1 mRNA level was associated with a lower median survival of patients in multiple tumor types." (PMID 31496918, 2019). "Consistent with this, spatial transcriptomic profiling revealed stronger expression of eIF4A1 and eIF4G1 in the metastatic sample than in the primary tumor sample." (PMID 41279557, 2025). "Based on our previous research, we found that the expression of EIF4G1 changes during tumor development." (PMID 38405671, 2024). "The translation initiation factor, EIF4G1, is highly expressed in a variety of tumors, and its ability to regulate the expression of numerous proteins has an important impact on tumor proliferation, migration, secretion of cytokines, and tumor angiogenesis." (PMID 38405671, 2024). "Herein, we found that regulating the level of EIF4G1 can affect the sensitivity of tumor cells to TNFSF10 by altering the expression of TNFSF10 receptors, which has good clinical prospects." (PMID 38405671, 2024). "Previously, our group found that EIF4G1 expression is significantly higher in NSCLC tissues than in paraneoplastic tissues and affects patient prognosis, such that high expression of EIF4G1 in tumor tissues predicts shorter patient survival." (PMID 38405671, 2024). "This suggests that EIF4G1 knockdown in the H1299 cell line affects the chemotaxis of macrophages towards tumor cells by regulating CXCL8." (PMID 38405671, 2024). "In vivo, it is possible that macrophages are more likely undergo chemotaxis toward tumor tissues with low EIF4G1 expression, thereby promoting inflammatory responses in tumor tissues." (PMID 38405671, 2024). "Depletion of EIF4G1 significantly decreased tumor growth in vivo compared with that noted in the vector cells." (PMID 36897548, 2023). "The analysis of LSCC adjacent and paired tumor tissues indicated that the expression levels of EIF4G1 in LSCC tumor tissues were higher than those of the adjacent tissues." (PMID 36897548, 2023). "The data show that EIF4G1 promotes tumor cell proliferation and the G1/S transition of cell cycle in LSCC, then the biological function of LSCC is effected by the AKT/mTOR pathway." (PMID 36897548, 2023). "FTO promoted OSCC tumorigenesis by enhancing the eIF4G1 stability, thereby decreasing the autophagic process and inducing tumor occurrence." (PMID 36582218, 2023). "In our study, high expression of WDR4, EIF4G1 and SLBP were significantly associated with a poor OS (p < 0.001) and increased tumor stem cell score in LUAD." (PMID 36226166, 2022). "In this study, we systematically investigated the prognostic value of EIF4G1 in BRCA, determined the association of EIF4G1 with tumor-infiltrating immune cells (TIICs) and immunotherapy response, and screened for potential drugs against BRCA." (PMID 36551184, 2022). "Immunohistochemistry (IHC) staining showed that the expression of Ki-67, MET, and eIF4G1 was much lower in circTMTC1 silence tumor tissues than that in sh-NC control tumor tissues." (PMID 35301291, 2022). "EIF4G1 was mainly localized in the cytoplasm of the specimens, and the staining was predominant in the tumor tissues." (PMID 36551184, 2022).